TLR2 (toll like receptor 2)
Diseases named in the same sentence as TLR2 in open-access papers (continued):
Sharing a sentence is not in itself a finding about the gene and the disease.
colitis (continued). "In animal studies, TLR2 expression and activation were sufficient to facilitate eosinophil recruitment and tissue eosinophilia of the large intestine in the context of experimental colitis." (PMID 25309051, 2014). "Similar to the TNBS-colitis model, activation of both TLR2 and TLR4 is seen in IBD." (PMID 23382912, 2013). "While mechanistic studies have not been reported for TLR1 and -6, TLR2 KO mice have been shown to be more susceptible to DSS colitis than WT controls." (PMID 24062746, 2013). "Colitis induction resulted in increased expression of TLR2 and TLR4 in epithelial cells." (PMID 23382912, 2013). "In fact, Tlr2 has been mostly studied in experimental models of overt colitis where it has been reported that Tlr2 regulates the synthesis of TFF3, a main component of the intestinal mucus, contributing to the protection of the intestinal mucosa and to its restitution after damage." (PMID 22242189, 2012). "However, we found that B6 WT CD4+CD25+Foxp3+ Treg efficiently suppressed T-cell-mediated colitis in both B6.RAG−/− or B6.RAG−/−.TLR2−/− recipients." (PMID 19950179, 2010). "Mice ablated of TLR2, TLR4, TLR9, or their common adaptor molecule MyD88, were more acutely susceptible to colitis induced by the chemical colitogen dextran sodium sulfate (DSS), due in part to impaired protective responses and reduced prostaglandin production." (PMID 20885960, 2010). "Furthermore, co-transfer of CD4+CD25+ Treg isolated from B6.TLR2–/– mice inhibited colitis development to a similar degree as B6 WT CD4+CD25+ Treg." (PMID 19950179, 2010). "may therefore have a confounding effect in mouse colitis models, particularly as H. muridarum was shown to engage TLR2 and NOD1, both of which are expressed in intestinal epithelial cells." (PMID 19401779, 2009). "Notably, severe bacterial OVA-specific colitis in NOD2-deficiency relies on the activation of TLR2 because mice double deficient in NOD2 and TLR2 display markedly less colonic inflammation and accumulation of OVA-specific Th1 cells in the colonic lamina propria." (PMID 39403381, 2024). "Additionally, a recent study demonstrated that Tlr1 and Tlr2 (but not Tlr6) knockout mice display increased intestinal permeability and pathogenic yeast colonisation in a colitis model." (PMID 37997696, 2023). "However, the importance of TLR2 signaling by B. fragilis has not been proven in colitis-associated CRC." (PMID 30429227, 2018). "In addition, we further perform IL-10-/- mice to clarify whether the BF through TLR2 /IL-10 pathway to alleviate DSS-colitis." (PMID 28683149, 2017). "For example, experimental studies in hosts knockout for TLR9, TLR4, and TLR2 have shown increased susceptibility to the development of a colitis induced by dextran sodium sulfate (DSS), as well as the protective role against DSS colitis induced by agonists of TLR2 and TLR4 supplement." (PMID 26090492, 2015). "Interestingly, the development of ovalbumin-induced colitis in mice deficient in nucleotide binding oligomerization domain 2 (NOD2), an intracellular pattern recognition receptor associated with increased susceptibility for CD, depends on TLR2-derived signals." (PMID 26067254, 2015). "These divergent results may highlight differential roles of TLR2 in chronic inflammation versus acute inflammatory models such as dextran sodium sulphate (DSS) colitis and the different immune cells and mediators driving these models over their respective timeframes." (PMID 25309051, 2014). "The role of TLR2 in colitis-associated colorectal cancer development is not well understood." (PMID 20885960, 2010). "However, recent studies suggesting a protective role of TLR2 signaling in experimental colitis." (PMID 18159247, 2007). "Several components of A. muciniphila have been shown to interact with TLRs, particularly TLR2 and TLR4, and subsequently contribute to the amelioration of inflammation in colitis mice." (PMID 41488633, 2025).
colitis (continued). "In this study, increased mRNA expressions of TLR2 and TLR4 were observed in the DSS colitis group compared to those in the normal group." (PMID 40333150, 2025). "TLR2 and TLR4 expressions were significantly higher in colitis mice compared to those in TA-administered normal mice." (PMID 40333150, 2025). "In a high-fat diet-induced colitis mouse model, DCA promotes macrophage differentiation toward the M1 phenotype via Toll-like receptor 2 transduction via the M2 muscarinic receptor, leading to increased production of pro-inflammatory cytokines." (PMID 36819995, 2023). "Clostridium butyricum triggers IL-10 production from intestinal macrophages via the TLR2/MyD88 signaling pathway and prevents mice from DSS-induced colitis." (PMID 35967333, 2022). "Our data show that BB1 causes an increase in mouse intestinal barrier function in a TLR-2-dependent manner and prevents the DSS-induced increase in colonic permeability and the subsequent development of colitis." (PMID 34360835, 2021). "A recent study showed that Tlr4-, Tlr2-, or Myd88-knockout mice exposed to dextran sulfate sodium (DSS) show more severe colitis than wildtype mice." (PMID 34075172, 2021). "After curcumin treatment, the protein levels of TLR2, TLR4, MyD88, NF-κBp65, p38MAPK, and AP-1 in the colonic tissues of colitis mice were significantly reduced." (PMID 34567209, 2021). "This study showed that expression of TLR2, TLR4, TLR9, and MyD88 mRNA was significantly increased in colonic tissues of DSS-induced colitis mice relative to the normal control mice." (PMID 33193406, 2020). "B. fragilis PSA induces the differentiation of IL-10 producing FoxP3+ Tregs in mice in a TLR2-dependent manner, which can protect against TNBS-induced colitis and experimental colitis induced by Helicobacter hepaticus." (PMID 32351514, 2020). "Previous studies reported that the activation of TLR2 and TLR4 expression on macrophages and dendritic cells was involved in the pathogenesis of mouse colitis." (PMID 31921214, 2019). "In the TNBS-induced colitis model, VIP treatment exerts a time-course inhibition of TLR2 and TLR4 expression in colon epithelial and mononuclear cells." (PMID 31861827, 2019). "For example, it was found that pDCs detect polysaccharide A from Bacteriodes fragilis via TLR2 and induce Tregs, which produce IL-10 leading to protection against trinitrobenzenesulfonic acid (TNBS)-induced colitis." (PMID 29570694, 2018). "Similar to the findings for PSA and B. fragilis, curli fibers (amyloid fibers in enteric biofilms) are recognized by TLR2, result in IL-10 production, and ameliorate TNBS-induced colitis." (PMID 29515999, 2018). "To study the influence of bacterial antigen stimulation on the expression of miR-146a and immune activation through TLR2 and TLR4 we set up an experiment in which DSS colitis was induced in TLR2 and TLR4 knock out mice." (PMID 30478292, 2018). "In order to investigate the Toll-like receptor-2 (TLR2), TLR4, and interleukin 10 (IL-10) molecular signaling pathways involved in BF-mediated prevention of dextran sulfate sodium (DSS)-induced colitis." (PMID 28683149, 2017). "In this study, we showed that oral administration of Hsp65-LL prevented colitis development in mice and induced CD4+Foxp3+/CD4+LAP+ Tregs in a TLR2/IL-10-dependent fashion." (PMID 28194152, 2017). "Supporting these findings, the immunomodulatory effect of a polysaccharide A from Bacteroides fragilis was directly correlated with TLR2-signalling and increased FoxP3+Treg cells secreting IL-10 in an experimental model of TNBS-induced colitis." (PMID 25853847, 2015). "In this study, our results have shown that Medilac-S alleviated the protein and mRNA expressions of TLR2, TLR4, and TLR9 in the colon mucosa in experimental colitis." (PMID 25276470, 2014). "While TLR2 and TLR4 were up-regulated, TLR5 was significantly down-regulated in our TNBS-colitis model." (PMID 23382912, 2013).
colitis (continued). "TLR2 and TLR4 up-regulation in epithelial cells in this TNBS-colitis model as well as the cytokine up-regulation indicate bacterial activation of mucosal defense and inflammation." (PMID 23382912, 2013). "Similar suppression of colitis was observed when both naYve CD4+CD45RBhi T cells and CD4+CD25+ Treg isolated from B6.TLR2–/– mice were co-transferred into B6.RAG–/– recipients." (PMID 19950179, 2010). "For example, Clostridium butyricum and Bacteroides fragilis-derived polysaccharide A (PSA) have been shown to enhance IL-10 production in macrophages and Treg cells, respectively, through Toll-like receptor 2 (TLR2)-dependent signaling, ultimately contributing to the amelioration of colitis." (PMID 41511071, 2026). "The LA1 effect on TJ barrier function was shown to be mediated by the Toll-like receptor-2/TLR-1 and TLR-2/TLR-6 heterodimeric complex and had a protective effect against dextran sodium sulfate (DSS)-induced colitis in wild-type mice, where these effects were abolished in TLR-2 knockout mice." (PMID 41403703, 2025). "Mechanistically, butyrate has been demonstrated to activate Toll-like receptor 2 (TLR2)-mediated TGF-β expression in colonic dendritic cells, thereby promoting regulatory T cell (Treg) differentiation and conferring protection against colitis." (PMID 40152582, 2025). "In normal mice, TA administration increased the expression of TLR4, while in colitis mice, TA did not affect the mRNA levels of TLR2 and TLR4." (PMID 40333150, 2025). "Acute colitis was induced in wild-type (WT), TLR2 knockout (KO), TLR4 KO, and TLR9 KO mice by administrating the mouse pathogen C. rodentium, then colitis severity was evaluated based on body weight changes, pathology, and mucosal cytokine gene expression at two weeks after infection (acute phase)." (PMID 41293152, 2025). "Previous studies have shown that TLR-2 and NOS-2 expression decreases with anti-inflammatory therapies and that the dysregulation or deletion of these genes is crucial for both IBD pathogenesis and attenuation of DSS induced colitis severity in mice." (PMID 39275347, 2024). "The role of TLR1, TLR2 and TLR6 has been explored in the DSS-induced colitis model." (PMID 35630457, 2022). "Oral supplementation of LA1 showed TLR-2 dependent improvement of tight junction barrier and protection against intestinal inflammation, thereby preventing dextran sodium sulfate (DSS)-induced colitis in the mouse model." (PMID 35159419, 2022). "Moreover, a significant upregulation of TLR2 and TLR9 was observed in the group with active colitis." (PMID 35745756, 2022). "Additionally, curcumin significantly downregulated CD11b+F4/80+TLR4+ macrophages and the protein levels of TLR2, TLR4, MyD88, NF-κBp65, p38MAPK, and AP-1 in colitis mice." (PMID 34567209, 2021). "In non-sterile injury, as in DSS colitis, TLR2/TLR4 activation is driven both by PAMPs from commensal organisms and by LMW-HA released or exposed during injury." (PMID 33552081, 2020). "ICMT and RAS expressions were strongly increased in macrophages under the activation conditions of TLRs by lipopolysaccharide (LPS, a TLR4 ligand), pam3CSK (TLR2), or poly(I:C) (TLR3) and in the colons, stomachs, and livers of mice with colitis, gastritis, and hepatitis." (PMID 32422978, 2020). "In addition, these in vitro results were correlated with colonic IL-6 levels in DSS colitis because DSS is thought to disrupt the integrity of the mucosal barrier, which allows commensal bacteria to elicit TLR2 and TLR4 dependent inflammation." (PMID 31921214, 2019). "Using animal models of experimental colitis and arthritis it was shown that Gram-negative bacteria, possibly through the TLR2/IL-10 axis, reduced inflammation, whereas Gram-positive bacteria contributed to a more severe disease." (PMID 29503707, 2018). "It was also determined that the suppressive function of B. fragilis is mediated by TLR2 signaling during the development of several diseases, including colitis and nonintestinal diseases." (PMID 30429227, 2018).
colitis (continued). "Our results showed that BF ameliorated DSS-induced colitis through the TLR2 signal pathway, but not the TLR4 pathway." (PMID 28683149, 2017). "Unlike WT and TLR4-/- mice, the severity of DSS-colitis did not improve in TLR2-/- animals after BF colonization." (PMID 28683149, 2017). "Importantly, the clinical symptoms of colitis, such as diarrhea and bloody stools, appeared more rapidly in TLR1−/− and TLR2−/− mice than in wild-type and TLR6−/−C." (PMID 28289440, 2017). "However, DSS-induced colitis promoted an increased E. coli population in TLR1−/−, TLR2−/− and wild-type mice, but a decrease in TLR6−/− mice, regardless of C. albicans colonization." (PMID 28289440, 2017). "Together these data demonstrate that treatment with RA can protect against epithelial injury during acute colitis however, in the absence of TLR2, treatment with RA exacerbates disease." (PMID 25826367, 2015). "Our results indicate that S. Typhimurium ΔmsbB triggers exacerbated colitis in the absence of Nod1 and/or Nod2, which is likely due to increased TLR2 stimulation." (PMID 25423082, 2014). "In contrast, no changes in colitis severity was detected in mice harboring a disrupted TLR2 and MYD88 gene." (PMID 23372731, 2013). "TLR2 signaling is a protective factor against colitis-induced cancer and the absence of bacteria from the intestinal lumen results in polyp formation, as seen in studies with gnotobiotic mice." (PMID 22442665, 2012). "Protection from colitis was seen with VSL3 in TLR2 and TL4 knockout mice but not TLR9 mice validating the role of TLR9 signaling in the probiotic mechanism." (PMID 21995674, 2011). "The administration of deficient BMDCs conditioned by the probiotic strain, did not affect the course and severity of colitis, indicating the involvement of both the TLR2 and NOD2 signaling pathways in the control of the colitis." (PMID 17375199, 2007). "In a mouse model of colon inflammation, deoxycholic acid (DCA) was enriched by increased levels of Gram-positive bacteria, which promoted macrophage polarization toward the pro-inflammatory M1 phenotype (partially through TLR2 transactivated by the M2 muscarinic acetylcholine receptor)." (PMID 40185720, 2025). "In a mouse model of colonic inflammation, DCA was enriched after Gram-positive bacteria increased, and DCA then promoted macrophage polarization toward the pro-inflammatory M1 phenotype partially via TLR2 transactivated by the M2 muscarinic acetylcholine receptor." (PMID 40185720, 2025). "Similarly, the expressions of TLR2 and TLR9 were significantly upregulated in DSS-induced colitis." (PMID 35745756, 2022). "Moreover, the BB1 caused a marked enhancement in mouse intestinal TJ barrier in a TLR-2-dependent manner and protected against dextran sodium sulfate (DSS)-induced increase in mouse colonic permeability, and treated the DSS-induced colitis in a TJ barrier-dependent manner." (PMID 34360835, 2021). "The TLR2/1 agonist PAM3CSK4 (PAM3) induces human and murine monocytes to differentiate into immunosuppressive M2 macrophages, suggesting that PAM3 might be of benefit in the prevention/treatment of colitis." (PMID 32269253, 2020). "Therapeutics that compromise innate immune responses (TLR2 signaling, in particular) may not be beneficial to patients with colitis and can even worsen symptoms." (PMID 29441063, 2018). "For example, mice lacking TLR2 or TLR4 or the MyD88 adaptor protein involved in TLR signal transduction, exhibited increased susceptibility to the chemically induced dextran sulfate sodium (DSS) model of colitis 13–15." (PMID 19950179, 2010). "Importantly, we found no functional requirement for TLR2 in Treg function, as TLR2−/− Treg suppressed colitis as effectively as WT Treg." (PMID 19950179, 2010).
colitis (continued). "Similarly, E. coli Nissle 1917 ameliorated dextran sulfate-induced colitis and decreased the pro-inflammatory cytokine response in wild-type mice, but not in TLR2 or TLR4 knockout mice, which supports E. coli Nissle 1917 immunomodulation of host TLR2 and TLR4 signaling." (PMID 31847111, 2019). "Moreover, E. coli strain Nissle 1917 has been shown to ameliorate DSS colitis in C57BL/6 WT mice, but not in mice deficient in TLR2 or TLR4, suggesting that activation of both TLR2 and TLR4 signaling is pivotal for this microorganism in order to exert its beneficial effects." (PMID 24062746, 2013). "In this context, it is tempting to speculate that HIF-dependent induction of TLR2 and TLR6 may be part of hypoxia-elicited innate protection during epithelial inflammation and treatment with HIF-activators (such as DMOG) may be protective during colitis via TLR2 induction and signaling." (PMID 18159247, 2007). "In fact, the induction of colitis by DSS in the absence of TLR4, but not in the absence of TLR2, downregulated miR-146a expression." (PMID 30478292, 2018). "DSS-treatment for 8 days resulted in elevated mRNA levels of TLR4 and TLR7, while expression of TLR2 and TLR9 did not change in colitis mice." (PMID 27658624, 2016). "In the present study, the level of MHC-II was increased in DCs from the colitis mice without treatment along with over-expression of costimulatory molecules of DCs, including CD83, CD28, B7-DC, CD40, CD40 L, and TLR2." (PMID 27932984, 2016). "Noteworthy, in comparison with C57BL6 wild type mice treated with TNBS, the colonic FXR expression was up-regulated in TLR2−/− but not in TLR4−/− mice, despite the colitis was less severe in these mice." (PMID 23372731, 2013). "However, HnAb treatment decreased the mRNA expression of TLR4 and MyD88, but not that of TLR2, TLR9, compared to vehicle-treatment in DSS-induced colitis mice." (PMID 33193406, 2020). "In line with prior studies demonstrating that the absence of TLR2 signaling exacerbates chemically-induced and spontaneous colitis in mice, we found that TLR2KO mice lost more body weight than WT counterparts during induction of colitis as well as during recovery (closed and open circles)." (PMID 25826367, 2015).